FAM237B (family with sequence similarity 237 member B)
Description:
May activate the G protein-coupled receptor GPR83. Has orexigenic activity. Plays a role in the brain-adipose axis that controls feeding (By similarity).
Gene: Protein-coding gene on chromosome 7 (90,316,503 to 90,321,304, reverse strand). Ensembl gene ENSG00000283267.
Subcellular location: Secreted
Gene Ontology:
Biological process: regulation of feeding behavior
Cellular component: extracellular region
Homologues: Orthologues: chimpanzee FAM237B (97% identical), macaque FAM237B (95% identical), dog FAM237B (87% identical), pig FAM237B (82% identical), rat Fam237b (81% identical), mouse Fam237b (73% identical), tropical clawed frog FAM237B (34% identical). Paralogues in human: FAM237A (28% identical).
Diseases named in the same sentence as FAM237B in open-access papers:
FAM237B is named in the same sentence as 1 disease in open-access papers, as found by Europe PMC text mining. Sharing a sentence is not in itself a finding about the gene and the disease. The quoted sentences say what the papers report.
Obesity (1 paper, 2024). Accumulation of substantial excess body fat. "Gene prioritisation considering SNP GERP scores, variant consequences, and allele comparison with other mouse lines identified seven novel obesity candidate genes: 4930441H08Rik, Aff3, Fam237b, Gm36633, Pced1a, Tecrl, and Zfp536." (PMID 38483771, 2024).